HGF (hepatocyte growth factor)
Diseases named in the same sentence as HGF in open-access papers (continued):
Sharing a sentence is not in itself a finding about the gene and the disease.
cancer (continued). "Since several growth factors can be simultaneously produced in cancer microenvironments, it is possible that HGF and EGFR ligands are co-expressed in EML4-ALK NSCLC cells." (PMID 24952482, 2014). "Among several oncogenic signaling pathways implicated in BCa progression is that of hepatocyte growth factor (HGF) and its cell surface receptor, Met, now targeted by 25 experimental anti-cancer agents in human clinical trials." (PMID 25335552, 2014). "The paracrine signaling pathway is activated by HGF secretion by stromal cells, whereas the autocrine signaling pathway is initiated by HGF that is generated from cancer cells." (PMID 25202379, 2014). "The antimigratory and anti-invasive activities of (-)-oleocanthal were associated with suppression of activation of Brk, paxillin, and Rac1 in response to HGF stimulation in MDA-MB-231 cancer cells." (PMID 24849787, 2014). "Studies show that during hypoxia, Met expression is increased through binding of HIF-1 to the Met promoter region to amplify HGF-dependent Met activation and signaling, facilitating cancer cell malignant progression." (PMID 26932375, 2014). "Previous studies have also shown that certain signaling pathways mediate increased cancer progression as result of the HGF/c-Met axis, typically the phosphoinositide 3-kinase (PI3K) and mitogen-activated protein kinase signaling pathways." (PMID 25202379, 2014). "The activation of c-Met with HGF is known to play an important role in cell proliferation in many kinds of cancer cells." (PMID 24849787, 2014). "For this reason, Met-targeted cancer therapies have been developed and several HGF/Met inhibitors, including HGF neutralizing antibodies, Met down-regulating antibodies and Met Tyrosine Kinase Inhibitors (TKIs), are currently exploited in clinical trials." (PMID 28548070, 2014). "Cancer cells often display dysregulation of HGF/Met system, including autocrine and paracrine HGF production (and hence Met activation), and transcriptional overexpression or amplification of the Met gene." (PMID 28548070, 2014). "By contrast, carcinogenesis or malignant phenotypes in other cancer types are potently inhibited by overexpressed HGF." (PMID 24604303, 2014). "GLI3, ARNT2 and HGF showed predominantly nuclear staining in some cancer cells, while in others, the staining was predominantly cytoplasmic." (PMID 24988459, 2014). "In cancer HGF is produced by malignant cells and by surrounding fibroblasts, and thus HGF acts on Met in an autocrine and paracrine manner." (PMID 25119536, 2014). "Overexpression of c-Met occurs via paracrine and autocrine stimulation of HGF, which in turn stimulates cancer cell progression." (PMID 25202379, 2014). "Hepatocyte growth factor/scatter factor (HGF/SF) plays critical roles in cancer progression through its specific receptor, MET." (PMID 25268161, 2014). "Recently, HGF was reported to induce resistance to various molecular-targeted drugs in various types of cancers with oncogene drivers." (PMID 24952482, 2014). "Because c-Met is inappropriately expressed in almost all types of human cancer, the HGF/c-Met signaling pathway should be an attractive target for cancer therapies." (PMID 24595237, 2014). "Our experiments demonstrated that targeting c-Met inhibited SW620 cell proliferation and migration, thus supporting the development of c-Met inhibitors and HGF/c-Met antagonists as anti-cancer drugs in colorectal malignancy." (PMID 25427200, 2014). "The HGF/Met axis has thus attracted great interest as a potential target in the development of novel cancer therapies." (PMID 26932375, 2014). "Hepatocyte growth factor (HGF) is a pleiotropic cytokine which can lead to cancer cell proliferation, migration and metastasis." (PMID 24716444, 2014). "Several approaches to inhibition of the HGF/c-Met pathway in cancer cells have been reported, such as antagonistic ligands to c-Met, antibodies against HGF or c-Met, and small molecule c-Met inhibitors." (PMID 24566328, 2014).
cancer (continued). "The present review will present a brief summary of evidence supporting the HGF/Met axis as a plausible target for cancer chemotherapy, and the role of tocotrienols in suppressing Met activation, signaling and HGF-induced EMT." (PMID 26932375, 2014). "Expression of TGFβ1 and HGF in inflammatory cells was also shown in regions adjacent to cancer nests." (PMID 24137336, 2013). "The level of phospho-AKT, which was found to be increased in HGF/EGF-stimulated cells after treatment with cetuximab alone reverted back to basal untreated values in the presence of MetHer1 in five cancer cell lines of different tissue origins." (PMID 23812422, 2013). "Such HGF-mediated modification of DC (i.e., tolerogenic DC) leads to an escape of cancer cells from immunological challenges, as suggested." (PMID 23296269, 2013). "Similar to ER cells, in untreated SR H2170 cells, we found a marked upregulation (20-fold) of p-p70S6K, a protein downstream of mTOR that is involved in cancer cell survival, and an upregulation was seen in cells treated with HGF and SU11274." (PMID 24223799, 2013). "We provided evidence in 2001 that not only NK4 but also anti-HGF antibody is useful for improving the prognosis of malignant tumors, using pancreatic cancer-bearing mice." (PMID 23296269, 2013). "As a result, cancer cells can invade from hypoxic to aerobic tissues through HGF-mediated motogenic actions." (PMID 23296269, 2013). "Because host microenvironments can have a profound effect on the chemosensitivity of cancers and because stromal fibroblasts are the major sources of HGF, we assayed HGF production by human fibroblast cell lines." (PMID 24386407, 2013). "Dysregulation of the c-Met receptor, or overexpression of its ligand, hepatocyte growth factor (HGF), has also been associated with an aggressive cancer cell phenotype and the EMT process." (PMID 23349823, 2013). "Overall, in addition to cell motility, the induction of MMP via HGF-Ets pathways is required for cancer invasion." (PMID 23296269, 2013). "Our previous study demonstrated that, in patients with NSCLC, HGF is primarily detected in cancer cells with acquired resistance to EGFR-TKIs, suggesting that the production of HGF by these cells occurs mainly via an autocrine mechanism." (PMID 23690929, 2013). "After examining the function of HGF by treating cancer tissues with it, which resulted in completely blocked EGFR tyrosine kinase activity." (PMID 23407898, 2013). "Serum levels of HGF are elevated in patients with recurrent malignant tumors, thus suggesting an endocrine HGF delivery system." (PMID 23296269, 2013). "Stroma-rich cancers, such as gastric scirrhous carcinoma, show a great invasive activity, due to the ability of fibroblasts to secrete HGF (i.e., paracrine pathway)." (PMID 23296269, 2013). "Although HGF affected the cancer cell morphology in OCUM-2MD3 and OCUM-12 cells, hypoxia-induced EMT was not inhibited by anti-HGF neutralizing antibody or c-Met inhibitor in either OCUM-2MD3 or OCUM-12 cells." (PMID 23690936, 2013). "In many tumors, HGF/SF acts as a stroma-derived factor that bind to its receptor Met to promote proliferation, invasion and metastasis of cancer cells." (PMID 24340011, 2013). "HGF has a direct effect on EC via the enhancement of cancer cell-EC contact via FAK phosphorylation." (PMID 23296269, 2013). "HGF promotes cancer metastasis via inducing vascular bed formation and enhancing chemokine-induced homing." (PMID 23296269, 2013). "Overall, it was shown that SF is identical to HGF, suggesting roles of HGF/SF during cancer metastasis." (PMID 23296269, 2013). "Flow cytometry analyses have shown that the combination of bufalin and gefitinib induced apoptosis of HCC827 cells, although HGF rendered EGFR mutant cancer cells resistance to apoptosis induced by EGFR-TKIs." (PMID 23533466, 2013).
cancer (continued). "In the present study, carcinoma cells and CAFs surrounding cancer nests markedly expressed TGFβ1 and HGF in ESCC when compared with that of precancerous lesions, particularly at the invasive edges of the carcinoma." (PMID 24137336, 2013). "These mutants clearly suppress HGF-induced cancer cell migration via the inhibition of MET tyrosine phosphorylation." (PMID 23296269, 2013). "HGF protects cancer cells from chemo drugs, such as Adriamycin, cisplatin and 5FU via the different mechanisms." (PMID 23296269, 2013). "Several lines of in vitro studies have indicated that HGF stimulates the scattering and migration of cancer cells." (PMID 23296269, 2013). "In this section, we will discuss the roles of HGF–MET pathways for cancer onset and development, with an interest in molecular mechanisms." (PMID 23296269, 2013). "Hepatocyte growth factor (HGF) has been demonstrated to stimulate cancer proliferation, migration, and metastasis." (PMID 23320110, 2013). "On the other hand, activation of MMPs is also involved in HGF-mediated cell motility in human cancer cells." (PMID 23320110, 2013). "Numerous types of carcinoma cells secrete soluble factors that induce HGF production in stromal cells (i.e., HGF-inducers)." (PMID 23296269, 2013). "Age, HGF (hazard ratio, 1.31; 95% CI, 1.04–1.65; P = 0.02), and total cholesterol were independent predictive markers for cancer death." (PMID 22672958, 2012). "In patients with cancer, hepatocyte growth factor (HGF) is elevated and is a predictor of prognosis." (PMID 22672958, 2012). "Immunoblot and immunohistochemistry with the anti-phospho-PKCζ or anti-phospho-CXCR4 antibody further confirmed that PKCζ-shRNA reduced the expression of phosphorylated PKCζ and HGF-induced phosphorylated CXCR4 in cancer cells of the MDA-MB-436 xenografts." (PMID 22242160, 2012). "For example, HA-mediated mitogenic signalling has been suggested to involve an interaction between CD44 and erbB family members whilst the v6 isoform (‘CD44v6’) is critically required for HGF/SF-mediated c-Met activation in human cancer cells." (PMID 23039365, 2012). "For cancer death, age, HGF, and total cholesterol (inversely) remained significant: after adjustment for confounding factors, the HRs by HGF quartile were 1.22 (95% CI, 0.53–2.83) for Q2, 1.19 (0.50–2.83) for Q3, and 2.21 (1.03–4.76) for Q4." (PMID 22672958, 2012). "Serum HGF was a predictor of cancer death in an apparently healthy population of community-dwelling Japanese." (PMID 22672958, 2012). "In conclusion, serum HGF was a predictor of cancer death in an apparently healthy community-dwelling Japanese population." (PMID 22672958, 2012). "For instance, VEGF, HGF and IL-8 significantly stimulate the proliferation, migration, and invasion of cancer cells." (PMID 22731825, 2012). "It has been definitively established that only cancer cells with specific genetic alterations, namely either met gene amplification or HGF autocrine loop maintain dependence on the met gene activation for transformation, i.e. remain met addicted." (PMID 22999213, 2012). "The HGF-cMet system is already a target for the development of clinical therapeutics for many diseases, including cancer." (PMID 22912808, 2012). "It is possible that participants with high baseline HGF levels experienced rapid growth and spread of cancer once they developed cancer." (PMID 22672958, 2012). "The prevalence of the activation of the HGF/c-Met in human malignancies has driven rapid growth in drug development to target this signaling axis for cancer therapy." (PMID 22639908, 2012). "Interaction between hepatocyte growth factor (HGF) and the Met receptor tyrosine kinase mediates development and progression of cancers." (PMID 22242160, 2012). "Hepatocyte growth factor/scatter factor (HGF/SF) is an important fibroblast-secreted protein that mediates development and progression of cancers." (PMID 22242160, 2012).
cancer (continued). "HGF/c-Met signaling regulates cellular motility, invasion, and metastasis in various types of human cancer." (PMID 22912725, 2012). "A strength of the present study is that it is the first prospective cohort study to show that HGF is a predictor of cancer death in apparently healthy adults." (PMID 22672958, 2012). "The established role of c-MET and HGF/SF in the initiation and progression of a variety of human cancers has stimulated an extraordinary effort into the development of c-MET specific TKIs, with many of these currently under investigation in patients." (PMID 22511956, 2012). "Overrepresented pathway analysis performed by Ingenuity Pathway Analysis at E11.5 and E19.5 identified common Nkx2-1 targeted pathways at both stages, such as ‘mechanisms of cancer’ and ‘HGF signaling’." (PMID 22242187, 2012). "Cancer patients are reported to have elevated serum levels of growth factors, namely hepatocyte growth factor (HGF), epidermal growth factor (EGF), transforming growth factor-beta (TGF-β) and insulin-like growth factor-1 (IGF-1), among others." (PMID 22432005, 2012). "Upon binding to its ligand, hepatocyte growth factor (HGF), the c-Met receptor initiates a signaling cascade leading to invasive growth and cancer cell dissemination." (PMID 22639908, 2012). "CAF produce growth factors, such as IGF and HGF, and directly interact with cancer cells to promote growth and survival." (PMID 23109879, 2012). "As observed with hematoxylin and eosin (H&E) and PCNA staining, HGF injection led to more intense infiltration of cancer cells into the lung and liver of MDA-MB-436 xenograft-bearing mice than did the PBS injection." (PMID 22242160, 2012). "In this system inhibition of the EGFR kinase with gefitinib or erlotinib abolished HGF induced proliferation and motility of some carcinoma cells." (PMID 23028720, 2012). "This study showed that the down-regulation of cell-cell contact molecules in claudin-low cancers is accompanied by changes in HGF signalling and apical sorting molecules." (PMID 21347235, 2011). "In cancer cells, activation of Met by HGF induces nuclear translocation of β-catenin, leading to activation of TCF/LEF-mediated gene transcription." (PMID 21535464, 2011). "In vitro assay using purified MDSC showed that TGF-β, EGF, and HGF signaling pathways are all used by MDSC to induce EMT in cancer cells." (PMID 21980263, 2011). "Tetraspanin CD82 forms a complex with c-Met and inhibits hepatocyte growth factor (HGF)-induced cancer cell migration by inactivation of small GTP-binding proteins in the Rho family, via c-Met adapter proteins." (PMID 21961047, 2011). "Overall, our results suggested that HGF is the major factor contributing to the differential effects of CAFs on cancer cell colony forming ability." (PMID 21249190, 2011). "For instance, TGF-β can directly induce oral squamous cancer cells to a myofibroblastic phenotype, and the TGF-β signaling by stromal myofibroblast can induce secretion of hepatocyte growth factor (HGF) which promotes cancer cell proliferation and invasion." (PMID 21880137, 2011). "Over-expression of HGF and c-Met has been reported to correlate with increased aggressiveness of tumors and a poor prognosis in cancer patients." (PMID 21575221, 2011). "HGF overexpression is detected in 45% of HNSCCs, suggesting that HGF functions predominantly in a paracrine manner to drive Met signaling in these cancers." (PMID 21776391, 2011). "Accordingly, growth factors such as TGF-β and hepatocyte growth factor (HGF, or its receptor c-Met) that are involved in cancer-stromal interactions and EMT have been well studied in order to develop therapeutic strategies targeting these factors." (PMID 24212624, 2011). "On cancer cells, HGF mostly acts as an inducer of cell migration and invasion as demonstrated in previous studies." (PMID 29147173, 2010).
cancer (continued). "Since Met-HGF/SF signaling is involved in the progression of so many human cancers, it has the potential for being a significant therapeutic target." (PMID 21049054, 2010). "G-DC share some characteristics with post-G DC 32, HGF-conditioned DC-like cells 36, DC-10 37,38 and DC conditioned with serum from cancer patients." (PMID 20957751, 2010). "TGF-β and HGF play significant roles as immune modulating growth factors both physiologically and in pathological states such as cancer." (PMID 21062439, 2010). "Currently, there are at least 12 Met and HGF/SF inhibitors in clinical trials; these range from small molecule inhibitors to monoclonal antibodies tested against a wide spectrum of cancers." (PMID 21049054, 2010). "Hepatocyte growth factor (otherwise known as scatter factor) is a protein factor that has a powerful effect on hepatocyte, cancer cells and endothelial cells." (PMID 29147173, 2010). "Activation of the Met receptor by its ligand, hepatocyte growth factor (HGF), has been shown to induce increased cell migration of keratinocytes and is implicated in cancer metastasis." (PMID 20687930, 2010). "MET, found originally to be involved in cancer metastasis, facilitates the signaling of hepatocyte growth factor (HGF)/scatter factor and its involvement in peripheral organ development and repair, immune function and gastrointestinal repair." (PMID 20029653, 2009). "The hepatocyte growth factor (HGF) receptor, c-Met, is strongly implicated in late-stage cancer progression and poor patient prognosis." (PMID 19439912, 2009). "The receptor tyrosine kinase, c-Met and its ligand hepatocyte growth factor/scatter factor (HGF/SF), have become leading candidates for targeted cancer therapies." (PMID 19796390, 2009). "HGF plays roles in organizing tissues during development and regeneration, but in cancer stimulates malignant cell invasive behaviour." (PMID 19272140, 2009). "As a functional consequence of multiple signaling pathway inhibition and interference with transcriptional regulation, ENMD-1198 significantly inhibited both EGF- and HGF-mediated cancer cell migration and invasiveness." (PMID 18651980, 2008). "Various targeted inhibitory strategies are being undertaken in drug development to antagonise MET/HGF signalling in human cancers, including small-molecule kinase inhibitors, antibodies to the ligand HGF, and receptor MET itself." (PMID 19238632, 2008). "Since its discovery in the late 1980s 1,2, hepatocyte growth factor (HGF) has been under intense investigation for its role in cancer." (PMID 17576468, 2007). "HGF initiates internal cellular signaling to the cancer cells, which allows the cells to invade and metastasize by combining cell proliferation, motility, morphogenesis, and cell survival." (PMID 17261188, 2007). "Together with overexpressed HGF receptor on cancer cells, this situation creates a two-way stimulation for cancer cells: paracrine stimulation (HGF generated by stromal cells) and autocrine stimulation (HGF generated by cancer cells themselves)." (PMID 17576468, 2007). "Given the broad functional spectrum of HGF and its receptor in cancer, targeting HGF, the HGF receptor, and signalling events has been an attractive option for cancer therapy." (PMID 17576468, 2007). "The unique niche for HGF is its double role in cancer: direct action on cancer cells to increase their aggressiveness, and direct action on endothelial cells to induce angiogenesis and lymphangiogenesis." (PMID 17576468, 2007). "In the cellular interaction between HGF and stromal cells, conditioned medium from cancer cells has recently been shown to be able to induce rapid clustering of fibroblasts and to initiate a necrotic process." (PMID 17576468, 2007). "The finding that cancer cells from epithelial origins show aberrant HGF transcripts and proteins is interesting and indicates that the source of HGF in the body is well beyond stromal." (PMID 17576468, 2007).